IER5 (immediate early response 5)
Description:
Plays a role as a transcription factor. Mediates positive transcriptional regulation of several chaperone genes during the heat shock response in a HSF1-dependent manner. Mediates negative transcriptional regulation of CDC25B expression. Plays a role in the dephosphorylation of the heat shock factor HSF1 and ribosomal protein S6 kinase (S6K) by the protein phosphatase PP2A. Involved in the regulation of cell proliferation and resistance to thermal stress. Involved in the cell cycle checkpoint and survival in response to ionizing radiation. Associates with chromatin to the CDC25B promoter.
Synonyms: SBBI48
Tractability: PROTAC: ubiquitination databases record sites on it.
Gene: Protein-coding gene on chromosome 1 (181,088,700 to 181,092,900, forward strand). Ensembl gene ENSG00000162783.
Subcellular location: Nucleus; Cytoplasm
Subcellular location (Human Protein Atlas): Nucleoplasm; Nucleoli
Gene Ontology:
Molecular function: identical protein binding; protein binding
Biological process: cellular response to heat; positive regulation of cellular response to heat; positive regulation of transcription by RNA polymerase II; regulation of cell population proliferation
Cellular component: cytoplasm; nucleus; protein phosphatase type 2A complex
Genetic constraint (gnomAD): Loss-of-function variants: 3 observed, 6.78 expected, observed/expected ratio (o/e) 0.44, 90% interval 0.2 to 1.14. That is too few expected variants to judge how well the gene tolerates losing a copy. Missense variants: 531 observed, 412.19 expected, observed/expected ratio (o/e) 1.29, 90% interval 1.2 to 1.38. Synonymous variants: 286 observed, 196.19 expected, observed/expected ratio (o/e) 1.46, 90% interval 1.32 to 1.61.
Homologues: Orthologues: chimpanzee IER5 (99% identical), macaque IER5 (95% identical), pig IER5 (79% identical), mouse Ier5 (73% identical), dog IER5 (40% identical), zebrafish ier5 (36% identical), tropical clawed frog ier5 (36% identical). Paralogues in human: IER5L (26% identical), IER2 (25% identical).
Diseases named in the same sentence as IER5 in open-access papers:
IER5 is named in the same sentence as 36 diseases in open-access papers, as found by Europe PMC text mining. Sharing a sentence is not in itself a finding about the gene and the disease. The quoted sentences say what the papers report.
breast carcinoma (3 papers, 2016 to 2025). "IER5 expression is associated with poor prognosis in glioma, bladder, and breast cancer patients." (PMID 40002205, 2025). "(iv) A meta analysis of the prognostic value of genes indicates that IER5 significantly connected with poor prognosis of bladder cancer, brain malignant tumor and breast cancer." (PMID 28430589, 2017). "In addition, an even higher association of IER5 and RBM23 and EIF4A2 were found in breast cancer patients (r = 0.75 and p < 0.0001 for RBM23, and r = 0.65 and p < 0.0001 for EIF4A2)." (PMID 26754925, 2016).
cervical cancer (3 papers, 2017 to 2025). A primary or metastatic malignant neoplasm involving the cervix. "Mechanistically, we confirmed that IER5 induced by radiation dose enhanced apoptosis of cervical cancer, was inversely associated with tumor size." (PMID 28430589, 2017). "Several previous studies have confirmed that IER5 is overexpressed and associated with high apoptosis rate in cervical cancer induced by radiation, alternatively, the high proportion of apoptosis promoted the radiosensitivity conferred by IER5 gene amplification." (PMID 28430589, 2017). "The IER5 gene is sensitive to radiotherapy in cervical cancer, and Cdc25B is an important cyclical regulatory protein of the G2/M transition in HeLa cells, which is critical to our understanding of cell proliferation and apoptosis." (PMID 40852688, 2025). "Despite this limitation, our findings highlight the role of IER5 in modulating Cdc25B expression postirradiation, suggesting a potential therapeutic strategy for cervical cancer." (PMID 40852688, 2025). "Previous quantitative realtime-PCR (qRT-PCR) assay was performed to identify expression of IER5 in cervical cancer biopsies receiving DDP-CCRT." (PMID 28430589, 2017). "TUNEL assay and western blot analysis indicated that IER5 promoted apoptosis, thus suppressing the tumor growth in cervical cancer tissues induced by irradiation." (PMID 28430589, 2017). "Our investigations found that IER5 level was markedly elevated in cervical cancer patients after being treated with irradiation, which indicated IER5 was closely dose induced." (PMID 28430589, 2017). "This study showed that there was a strong correlation between the expression of IER5 and the tumor size induced by irradiation, and the smaller tumor size of cervical cancer tissues, the greater variation of the IER5 expression." (PMID 28430589, 2017). "In conclusion, our studies indicate target IER5 is improved to be a potential radiosensitizer for developing effective therapeutic strategies against cervical cancer to radiotherapy and a predictive biomarker for radiosensitivity." (PMID 28430589, 2017). "Therefore, exploring the molecular mechanism of IER5-induced apoptosis in cervical cancer cells after radiotherapy is important." (PMID 40852688, 2025). "Currently, researchers have observed that IER5, as a promising radiosensitizer for the responses of advanced cervical cancer patients, has been proved plays an important role in the regulation of the cell cycle, cell apoptosis and radiosensitivity mechanism in various cells." (PMID 28430589, 2017). "IER5 may be a potential predictive biomarker for the patients with cervical cancer receiving radiotherapy, supporting the pursuit of clinical significance of IER5." (PMID 28430589, 2017). "IER5 could be a promising predictive biomarker for the responses of cervical cancer patients receiving concurrent chemoradiotherapy." (PMID 28430589, 2017). "Therefore, in this study, taken cervical cancer patients as the research object, the role of IER5 in apoptosis of cervical cancer tissues and its correlation with clinicopathological features were explored." (PMID 28430589, 2017). "Therefore, although the IER5 gene can increase the radiation sensitivity, it can also activate other related oncologic factors leading to the deterioration, finally, results in a variety of clinical outcomes of cervical cancer." (PMID 28430589, 2017).
bladder cancer (2 papers, 2016 to 2017). "Expression of IER5 and cancer-associated HSF1 target genes (RBM23 and EIF4A2) showed a significant association in bladder cancer (r = 0.64 and p < 0.0001 for RBM23, and r = 0.54 and p < 0.0001 for EIF4A2)." (PMID 26754925, 2016).
brain cancer (2 papers, 2016 to 2017). A primary or metastatic malignant neoplasm affecting the brain. "Search of a publicly available cancer microarray database (PrognoScan;32) revealed that higher IER5 expression is associated with poorer prognosis in bladder, breast and brain cancer patients." (PMID 26754925, 2016). "Interestingly, higher HSPA6 (the gene most strongly induced by IER5 expression) expression is also related to poorer prognosis, and we observed overall similar patterns of survival among bladder and brain cancer patients exhibiting high versus low IER5 and HSPA6 expression." (PMID 26754925, 2016).
glioma (2 papers, 2021 to 2025). A benign or malignant brain and spinal cord tumor that arises from glial cells (astrocytes, oligodendrocytes, ependymal cells). "High IER5 expression is associated with poor prognosis in bladder, breast, brain, and glioma patients." (PMID 40002205, 2025). "Another equally pivotal aspect of this study is the finding that IER5 expression is linked to the invading levels of diverse immune cells in glioma." (PMID 34222249, 2021). "Although our study revealed the association of IER5 with glioma, there were still some limitations that remain to be addressed." (PMID 34222249, 2021). "To predict the prognosis of glioma patients, we constructed a nomogram that integrated IER5 expression and independent clinical risk factors (WHO grade, IDH status, primary therapy outcome, age, and 1p/19q codeletion)." (PMID 34222249, 2021). "Moreover, we conducted IHC using a TMA to assess the association of the protein level of IER5 with the prognosis of individuals with glioma." (PMID 34222249, 2021). "Kaplan–Meier survival assessment showed that glioma individuals with high IER5 expression had a poorer prognosis in contrast with those with low IER5 expression (P < 0.001)." (PMID 34222249, 2021). "Herein, bioinformatics analyses of the prognostic significance of IER5 expression in glioma patients were carried out using high-throughput RNA-sequencing data from TCGA." (PMID 34222249, 2021). "Gene set enrichment analysis was carried out to determine the biological signaling cascades related to glioma by comparing the high- and low-IER5 expression datasets." (PMID 34222249, 2021). "Correlation of IER5 expression and clinical prognosis in glioma patients with different clinicopathological characteristics." (PMID 34222249, 2021). "We performed Kaplan-Meier survival assessment to explore the utility of IER5 expression levels in glioma patients stratified by clinicopathological characteristics." (PMID 34222249, 2021). "We used univariate Cox analysis to assess the relationship of IER5 expression with the clinicopathological characteristics of glioma patients." (PMID 34222249, 2021). "Our data suggest that IER5 expression can be utilized as a prognostic biomarker for the assessment of disease progression or as a prospective therapeutic target for glioma patients." (PMID 34222249, 2021). "IER5 overexpression in glioma patients was correlated with advanced clinicopathological characteristics (advanced WHO grade, WT IDH status, a primary therapy outcome of CR, age ≤ 60 years, and 1p/19q codeletion), short survival time, as well as poor prognosis." (PMID 34222249, 2021). "We explored IER5 protein levels by quantitative immunohistochemistry (IHC) in a tissue microarray (TMA) of glioma samples from patients with known clinical outcomes." (PMID 34222249, 2021). "All the results suggest that the potential of IER5 as a prognostic biomarker and treatment target in glioma patients." (PMID 34222249, 2021). "To predict glioma patient prognosis, we developed a nomogram consisting of the expression level of IER5 and clinicopathological characteristics." (PMID 34222249, 2021). "We also validated the prognosis value of IER5 in three independent datasets in Chinese Glioma Genome Atlas (CGGA)." (PMID 34222249, 2021). "We also analyzed the effect of the IER5 gene on glioma prognosis through multivariate Cox regression analysis." (PMID 34222249, 2021). "Our results suggest possible mechanisms by which IER5 regulates the infiltration of Th2 cells, along with γδ T cells in glioma patients." (PMID 34222249, 2021). "Using TMA containing samples from 180 glioma patients, the protein expression levels of IER5 were analyzed through IHC staining." (PMID 34222249, 2021). "Our findings illustrate that IER5 is an independent prognostic marker for glioma." (PMID 34222249, 2021). "In summary, IER5 likely plays a core role in the modulation of immune cell infiltration in glioma." (PMID 34222249, 2021).
glioma (continued). "All these results indicate that the expression of IER5 is significantly up-regulated in glioma." (PMID 34222249, 2021). "Nonetheless, the expression level of IER5 and its prognostic significance in glioma patients remain unclear." (PMID 34222249, 2021). "Herein, we established that IER5 plays a critical role in glioma progression and prognosis, which might be an important biomarker for the prognosis of glioma patients." (PMID 34222249, 2021). "However, further studies should be conducted to validate the molecular mechanism and the clinical application of IER5 as a prognostic indicator or therapeutic target for glioma patients." (PMID 34222249, 2021). "In conclusion, the IER5 expression might serve as a reliable molecular marker for patient survival in glioma." (PMID 34222249, 2021). "Therefore, we will perform laboratory experiments to further validate our results and investigate the mechanism of IER5 in glioma." (PMID 34222249, 2021). "In addition, we analyzed the PPI network by Metascape to better understand the role of IER5 in the development of glioma." (PMID 34222249, 2021). "It is interesting that the Kaplan–Meier survival analysis illustrated a remarkable association of IER5 expression level with OS in WT IDH status gliomas but not mutant gliomas in patients with 1p/19q codeletion gliomas but not in patients without 1p/19q codeletion." (PMID 34222249, 2021). "Data on the expression levels of proteins other than IER5 in patients were lacking, and we could not explore the direct mechanism of IER5 in the development of glioma." (PMID 34222249, 2021). "We explored the gene expression level of IER5 in glioma and non-malignant brain tissues." (PMID 34222249, 2021). "However, there are no reports available about the relationship between IER5 and glioma." (PMID 34222249, 2021).
leukemia (2 papers, 2011 to 2025). A malignant (clonal) hematologic disorder, involving hematopoietic stem cells and characterized by the presence of primitive or atypical myeloid or lymphoid cells in the bone marrow and the blood. "We first determined the relative expression of IER5 mRNA in the leukemia cell lines KG-1, Kasumi-1, U937 and YRK2." (PMID 22132193, 2011). "We found that IER5 expression inhibited the proliferation of both leukemia cell lines and of leukemic blast cells derived from AML through the transcriptional repression of Cdc25B." (PMID 22132193, 2011). "This analysis indicated that the expression of IER5 mRNA in the TMPP-treated leukemia cells was increased 1.78 to 2.29-fold relative to its expression in untreated cells." (PMID 22132193, 2011). "In this study, we investigated the function of IER5 in leukemia cell proliferation." (PMID 22132193, 2011).
mood disorder (2 papers, 2022). A cognitive disorder a disturbance in which the person's mood is hypothesized to be the main underlying feature. "We found a significant overlap for 6 hub genes (ADM, CITED2, IER5, NFKBIZ, SERTAD1, TNF) with similar co-expression and dysregulation patterns associated with mood disorder." (PMID 35386281, 2022). "In addition to this set of genes, we also noted the immediate early response 5 gene (Ier5), which appears upregulated in our meta-analysis, was previously found dysregulated in peripheral blood mononuclear cells of unmedicated mood-disorder patients compared to healthy controls." (PMID 36362329, 2022).
acute myeloid leukemia (1 paper, 2011). Acute myeloid leukemia (AML) is a group of neoplasms arising from precursor cells committed to the myeloid cell-line differentiation. "In this study, we investigated the involvement of IER5 in the cell cycle and in cell proliferation of acute myeloid leukemia (AML) cells." (PMID 22132193, 2011).
cervical tumors (1 paper, 2017). "Radiation treatment increased the expression of IER5, which promoted cellular apoptotic death in cervical tumors." (PMID 28430589, 2017).
colon cancer (1 paper, 2020). "Since PAF1 is highly expressed in CC tissue and PAF1 promotes the release of Pol II on the IER5 promoter in colon cancer cells, we decided to study further the relationship between PAF1 and IER5 in CC cells." (PMID 32471508, 2020).
colorectal cancer (1 paper, 2025). A primary or metastatic malignant neoplasm that affects the colon or rectum. "In addition to IER5, IER5L and IER2—two homologues of IER5 with structural similarity —are also highly expressed and promote tumor progression, metastasis, and invasion in various cancers including prostate cancer, non-small cell lung cancer, melanoma, and colorectal cancer." (PMID 40002205, 2025).
esophageal cancer (1 paper, 2016). A primary or metastatic malignant neoplasm involving the esophagus. "We took the OE33 esophageal cancer cell line, as it expressed relatively high levels of IER5, and analyzed the effect of IER5 knockdown under both adherent and suspension cell culture conditions." (PMID 26754925, 2016).
gastric cancer (1 paper, 2025). A primary or metastatic malignant neoplasm involving the stomach. "IER5 and its family members IER5L and IER2 have been reported to be overexpressed in many cancers including ovarian, hepatic, lung, and gastric cancers." (PMID 40002205, 2025).
HCMV infection (1 paper, 2016). "According to this model, HCMV infection stimulates IER5 expression, which in turn inhibits CDC25B expression and CDC25B-dependent CDK1 activation, contributing to IE1 transcription and lytic viral replication." (PMID 27824944, 2016). "The identification of IER5 as a target of miR-UL148D and its role in the regulation of CDC25B are also supported by the inverse correlation between IER5 and CDC25B expression that was observed during HCMV infection in host cells." (PMID 27824944, 2016). "Here, we showed that a HCMV-encoded miRNA, miR-UL148D, robustly accumulates during late stages of experimental latent HCMV infection in host cells and promotes HCMV latency by modulating the immediate early response gene 5 (IER5)-cell division cycle 25B (CDC25B) axis in host cells." (PMID 27824944, 2016).
myeloid leukemia (1 paper, 2025). A clonal proliferation of myeloid cells and their precursors in the bone marrow, peripheral blood, and spleen. "The authors proposed that IER5 can competitively bind to a Cdc25B promoter transcription factor-binding site in myeloid leukemia cells, thereby releasing transcription factors, such as NF-YB and p300, and inhibiting transcription." (PMID 40852688, 2025).